MUC13 (mucin 13, cell surface associated)
Diseases named in the same sentence as MUC13 in open-access papers (continued):
Sharing a sentence is not in itself a finding about the gene and the disease.
liver cancer (2 papers, 2023). An epithelial or non-epithelial malignant neoplasm that arises from the liver. "Recent studies reported MUC13-mediated activation of Wnt/β-catenin signaling in liver cancer, cross-talk of β-catenin, and Hippo-YAP1 signaling pathways in cancer." (PMID 37793774, 2023). "A recent study indicates that MUC13 plays a role in β-catenin-mediated Wnt signaling in liver cancer." (PMID 37793774, 2023). "Previous studies showed that the increased MUC13 expression led to nuclear localization of β-catenin, which decreased overall survival in liver cancer patients." (PMID 37793774, 2023).
pancreatic adenocarcinoma (2 papers, 2007 to 2020). "These genes include many not previously associated with pancreatic adenocarcinoma, such as galectin-4 (LGALS4), mucin 13 (MUC13), secretory leukocyte protease inhibitor (SLPI), collagen 17A1 (COL17A1), and ropporin 1-like (ROPN1L)." (PMID 17389914, 2007).
ulcerative colitis (2 papers, 2021 to 2024). An inflammatory bowel disease involving the mucosal surface of the large intestine and rectum. "MUC13 mRNA expression is upregulated in the inflamed colon in individuals with IBD and a mutation in the MUC13 cytoplasmic tail was shown to be associated with the development of ulcerative colitis." (PMID 38345099, 2024).
Chronic colitis (1 paper, 2023). A chronic inflammatory disease of the large intestine (colon, cecum and rectum). "Indeed, we have recently described strong positive associations between aberrant Muc1 and Muc13 expression, increased intestinal barrier permeability and the altered expression levels of junctional and polarity proteins during acute and chronic colitis in dextran sodium sulphate (DSS)-treated mice." (PMID 37174625, 2023). "Jam2 and Ocln mRNA expression was significantly increased in both wildtype and Muc13−/− mice upon acute and chronic colitis, respectively, whereas Tjp2 mRNA expression was only elevated in Muc13−/− mice after the first DSS cycle." (PMID 37174625, 2023). "Differences in mRNA expression of cell polarity subunits were only observed for Scrib and aPkcz after the third cycle of DSS administration in both wildtype and Muc13−/− mice whereas expression of Ceacam 1, and Tlr4 mRNA was found to be significantly altered upon chronic colitis." (PMID 37174625, 2023).
clear cell renal cell carcinoma (1 paper, 2017). "The purpose of this study is to evaluate the prognostic value of MUC13 expression in patients with non-metastatic clear cell renal cell carcinoma (ccRCC) after surgical resection." (PMID 27911274, 2017).
diabetic cardiomyopathy (1 paper, 2026). Diabetic cardiomyopathy is a disorder of the heart muscle in people with diabetes. "In addition, this study suggests that MUC13 may be involved in other cellular processes such as apoptosis, autophagy, senescence, calcium signaling, microRNA activity, lysosomal function, and diabetic cardiomyopathy." (PMID 42028237, 2026).
esophageal squamous cell carcinoma (1 paper, 2017). Esophageal squamous cell carcinoma (ESCC) is a type of esophageal carcinoma (EC) that can affect any part of the esophagus, but is usually located in the upper or middle third. "Previous study demonstrated that blockage of MUC13 decreased sensitivity of esophageal squamous cell carcinoma cell lines to paclitaxel." (PMID 27911274, 2017).
esophageal tumor (1 paper, 2023). "The tumor xenograft growth assay was used to confirm the influence of MUC13 knockdown on the growth of esophageal tumors in vivo." (PMID 37395858, 2023).
influenza (1 paper, 2019). An acute viral infection of the respiratory tract, occurring in isolated cases, in epidemics, or in pandemics; it is caused by serologically different strains of viruses (influenzaviruses) designated A, B, and C, has a 3-day incubation period, and usually lasts for 3 to 10 days. "Quantitative real-time RT-PCR analysis of MUC15, MUC13 and MUC3A gene mRNA expression in hNECs infected with seasonal influenza H1N1, H3N2, and B, with uninfected control subjects as baseline (n = 4) and using PGK1 as the internal control." (PMID 31307416, 2019).
intestinal infections (1 paper, 2021). "The importance of the constitutive expression of mucins has been highlighted by mouse models deficient of MUC1, MUC2, and MUC13, revealing elevated susceptibilities towards intestinal infections, inflammations and spontaneous tumors." (PMID 34685068, 2021). "Yet, further research is required to clarify whether the alterations of MUC1, MUC2 and MUC13 expression are physiologically relevant for the susceptibility towards intestinal infections and inflammations." (PMID 34685068, 2021).
intraductal papillary mucinous neoplasms (1 paper, 2023). "In another study, analysis of EVs using a digital extracellular vesicle screening technique (DEST) reported the presence of a panel of mucins, including MUC1, MUC2, MUC4, MUC5AC, MUC6, and MUC13, in a cohort of 133 patients harboring intraductal papillary mucinous neoplasms (IPMN)." (PMID 36980526, 2023).
intrahepatic cholangiocarcinoma (1 paper, 2026). A carcinoma that arises from the intrahepatic bile duct epithelium in any site of the intrahepatic biliary tree. "MUC13 interacts with EGFR to induce PI3K/AKT signaling through EGFR and its internalization inhibition, thus promoting the metastasis of intrahepatic cholangiocarcinoma (ICCA)." (PMID 41513618, 2026).
Kabuki syndrome (1 paper, 2022). Kabuki syndrome (KS) is a multiple congenital anomaly syndrome characterized by typical facial features, skeletal anomalies, mild to moderate intellectual disability and postnatal growth deficiency. "We also identified two other variants in this line before the non-recombinant region was fully defined; a 27 bp inframe deletion in the Kmt2d gene which underlies Kabuki syndrome in humans, and a missense mutation in the gene Muc13." (PMID 35296311, 2022). "We found two such mutations in the process of sequencing the MDLY (ttch) mice: a missense mutation in Muc13 and a deletion in the Kabuki syndrome gene Kmt2d (also known as Mll2), neither of which affected hearing nor had any obvious effect on homozygotes." (PMID 35296311, 2022).
lymph node metastasis (1 paper, 2021). "Furthermore, MUC13 overexpression was correlated with an increase in lymph node metastasis in vivo, supporting that MUC13 likely plays a role in these processes 43-45." (PMID 34522225, 2021).
malaria (1 paper, 2019). Malaria is a serious and sometimes fatal disease caused by a parasite that commonly infects a certain type of mosquito which feeds on humans. "Therefore, MUC13 may serve as a universal biomarker for Plasmodium infection, upregulated regardless of the species of infecting malaria parasite." (PMID 30700707, 2019).
meningioma (1 paper, 2024). A generally slow growing tumor attached to the dura mater. "In silico, MUC1, MUC3, MUC4, and MUC13 were highly expressed in meningiomas (GEO database series GSE16581)." (PMID 38274327, 2024). "In the GEO database, the respective mRNA expressions of MUC1, MUC3, MUC4, and MUC13 was detected in Grade I, Grade II, and Grade III meningiomas." (PMID 38274327, 2024).
metastatic tumors (1 paper, 2023). "Using a commercially available (#CO953; BioMax) CRC tissue microarray, we found that 80% of metastatic tumors (n = 10) showed nuclear expression of MUC13 and YAP1." (PMID 37793774, 2023).
mucinous ovarian carcinoma (1 paper, 2024). An invasive malignant neoplasm that arises from the ovary and is characterized by the presence of malignant epithelial cells that contain intracytoplasmic mucin and may resemble the epithelial cells of the endocervix or gastrointestinal tract. "Genes such as MUC2, MUC5AC, MUC6, and MUC13, as well as the predominant intracellular presence of mucin, appear to be involved in the development and recurrence of mucinous ovarian carcinoma and can be used to differentiate between primary ovarian and metastatic lesions." (PMID 39598188, 2024).
nematode infection (1 paper, 2013). "In contrast to clearance of nematode infection, onset of clearance of C. rodentium was preceded by an early increase in Muc1, Muc2, Muc4 and Muc13 mucin transcript levels that had returned to pre-infection levels at least four days prior to clearance." (PMID 24386378, 2013).
ovarian tumors (1 paper, 2009). "Furthermore, our laboratory has recently identified the aberrant expression of a novel transmembrane mucin, MUC13, in ovarian tumor samples compared to normal/benign ovarian tissue samples." (PMID 20034397, 2009). "The much higher expression of mucins (MUC1, MUC4, MUC5AC, MUC13 and MUC16) in ovarian tumors compared to the surrounding normal tissues can be exploited for the purpose of radioimmunodiagnosis (RID) and radioimmunotherapy (RIT)." (PMID 20034397, 2009).
parasite (1 paper, 2019). "A final question is whether the MUC13 could be a clinically relevant biomarker of parasite infection." (PMID 30700707, 2019).
Stroke (1 paper, 2019). Sudden impairment of blood flow to a part of the brain due to occlusion or rupture of an artery to the brain. "Interestingly, gene expression of key components that form the mucus layer, mucin 2 (Muc2), mucin 4 (Muc4) and mucin 13 (Muc13) was decreased only in the older mice, but not in young mice, after stroke." (PMID 31199577, 2019).
tumor (43 papers, 2011 to 2025). "Combination of MUC13 knockdown and 5FU chemotherapy caused tumor regression in a CRC xenograft model." (PMID 33808549, 2021). "High MUC13 expression associated with tumor encapsulation, tumor size, venous invasion, tumor stage, and poor outcome of patients." (PMID 31991677, 2020). "The results demonstrate that miR-145-induced downregulation of MUC13 is associated with slower growth of PanCa cell lines, gemcitabine chemo-sensitivity and tumor growth reduction in pancreatic xenograft mice model." (PMID 25277192, 2014). "Our study provides compelling evidence that expression of miR-145 causes suppression of tumor growth through the inhibition of MUC13 expression." (PMID 25277192, 2014). "AGR2, FXYD3, TFF1, and MUC13 are associated with increased tumor grade." (PMID 39682235, 2024). "Interestingly, we observed a different mucin isoform pattern between soft and hard mucin tissues, with MUC13 being the only membrane-associated mucin found to be altered, making it a potential candidate to be considered as a cellular tumour marker or cellular therapeutic target." (PMID 38750435, 2024). "In addition, overexpression of MUC1 or MUC13 rescued GSDME-deficiency-retarded tumour growth." (PMID 35292781, 2022). "Protein-level validation, conducted via CPTAC and HPA databases, corroborated elevated MUC13 expression in tumor vs. normal tissues." (PMID 39309442, 2024). "Significantly, a positive correlation was observed between the protein expression levels of RUNX1 and MUC13 in CRC tumor tissues." (PMID 39309442, 2024). "A significant upregulation of MUC13 was detected in tumor samples relative to matched normal ones, with an unpaired t-test confirming statistical significance (P<0.0001)." (PMID 39309442, 2024). "In the tumor tissue of the TH mice, an increase in Cldn2 expression was observed, followed by a decrease in Cldn7 and Muc13 expression." (PMID 39063041, 2024). "The spatial transcriptomic analysis unveiled a distinctive pattern in the tumormicroenvironment, where both GPC3 and MUC13 were highly expressed in tumor samplescontrasting sharply with their complete absence in the control sample." (PMID 39872360, 2024). "Both datasets indicated significant upregulation of MUC13 in tumor samples as compared to normal controls." (PMID 39309442, 2024). "Our studies describe how MUC13 facilitates metastasis after disseminating tumor cells from the primary tumor site by targeting YAP1 and influencing its nuclear translocation, followed by the activation/expression of pro-survival/metastasis-associated genes." (PMID 37793774, 2023). "Next, the differential expression of MUC13 between tumor tissues and normal tissues and the survival prognostic significance of MUC13 was determined by Oncomine database and the Kaplan–Meier plotter, respectively." (PMID 37395858, 2023). "IHC further confirmed the differential expression of CIDEC, EPS8L3 and MUC13 in tumor tissues and adjacent normal tissue." (PMID 37978443, 2023). "It has been found that MUC13 is overexpressed in a variety of tumor cells and acts a vital role in the invasiveness and malignant progression of several types of tumors." (PMID 37395858, 2023). "The expression of CIDEC in tumor tissue was significantly lower than that in adjacent normal tissues, while the expression of EPS8L3 and MUC13 was significantly higher in tumor tissues." (PMID 37978443, 2023). "In a small cohort of human CRC patient tissues, YAP1 and MUC13 showed increased expression in tumor samples (stages I, II, III, and IV)." (PMID 37793774, 2023). "These aberrantly expressed glycoproteins, including MUC1, MUC4, and MUC13 play important roles in tumor progression and treatment and are commonly referred to as tumor-related glycoproteins." (PMID 36118865, 2022). "Knockout of either MUC1 or MUC13 retarded tumour growth, but the knockout of both achieved the greatest tumour regression." (PMID 35292781, 2022).
tumor (continued). "Consistently, YBX1, MUC1 and MUC13 were upregulated in tumour tissues of patients compared to the paracancerous tissues." (PMID 35292781, 2022). "MUC13 was markedly elevated in 93.8% of patients with ICC relative to the corresponding adjacent non-tumor tissues, and the upregulation of MUC13 was closely correlated with reduced OS and PFS of patients with CC." (PMID 32708604, 2020). "The tumor tissue samples were further analyzed for Immunohistochemistry (IHC) expression of MUC13 levels." (PMID 31906106, 2019). "We have previously shown that miR-145 expression inversely correlates with MUC13 expression in PanCa cells and human tumor tissues." (PMID 31906106, 2019). "In the case of MUC13, overexpression was detected in 44% of HCC cases and was significantly associated with tumour size, stage, encapsulation, venous invasion and poor outcome." (PMID 30875782, 2019). "Previously, we have shown that tumor suppressor miR-145 targets 3′ UTR of MUC13 and, thus, downregulates MUC13 protein expression in PanCa cells." (PMID 31906106, 2019). "Data was also presented to show that MUC13 plays significant role in tumor progression by facilitating invasion, metastasis, and cellular motality with a positive influence of tumorogenic pathways." (PMID 31689930, 2019). "This signifies a critical role of MUC13 in tumor microenvironment favoring the development of a more aggressive and invasive phenotype." (PMID 29467405, 2018). "We observed that MUC13 was not only expressed on the apical surface but also located in the cytoplasm and in the nucleus of tumor cells." (PMID 27911274, 2017). "The tumor tissue samples were further analyzed for the expression of miR-145 levels, MUC13 and HER2 by in situ hybridization (ISH) and immunohistochemistry (IHC)." (PMID 25277192, 2014). "The present study provides important insights into the tumor suppressor role of miR-145 in a well-known tumor-promoting network that includes MUC13." (PMID 25277192, 2014). "This clearly suggests that miR-145 silences the MUC13 expression and regulates the expression of its critical tumor target genes that are involved in pancreatic pathogenesis." (PMID 25277192, 2014). "Cluster II contained genes associated with tumor progression and metastasis, including HOXA9, MUC13, and members of the GAGE and CT-45 families." (PMID 21333016, 2011). "It is likely that the high Cldn2 expression in the TH animals promoted intestinal epithelial tissue regeneration, which was highly sensitive to AOM and DSS, and inflammation accompanying tumor growth led to a decrease in the number of goblet cells and, as a consequence, Muc13 expression." (PMID 39063041, 2024). "Importantly, this protocol also allowed us to identify MUC13 as a potential tumour cell marker in PMP." (PMID 38750435, 2024). "Similarly, upon quantifying tumor weights, the findings distinctly emphasized the inhibitory effect of MUC13 downregulation on the tumorigenic capabilities of RUNX1 overexpression." (PMID 39309442, 2024). "In TH mice, CAC was characterized by a decrease in Muc13 and Cldn7 expression and an increase in Cldn2 expression in the tumor tissue of the distal colon in comparison with the control group, while the expression of Muc13 and Cldn7 in the peritumoral area was higher relative to the tumors." (PMID 39063041, 2024). "In addition, RT-PCR results displayed that CIDEC was significantly reduced in tumor tissues, MUC13 was significantly increased in tumor tissues, EPS8L3 showed an up-regulated tendency, while PLEKHS1 was down-regulated in tumor tissues." (PMID 37978443, 2023). "Interestingly, tumor samples that showed nuclear MUC13 expression also demonstrated higher YAP1 expression." (PMID 37793774, 2023). "Furthermore, exogenous expression of MUC1 and MUC13 rescued the ability of YBX1−/− PDAC cells to grow a tumour in the pancreas." (PMID 35292781, 2022).